MT2A (metallothionein 2A)
Diseases named in the same sentence as MT2A in open-access papers (continued):
Sharing a sentence is not in itself a finding about the gene and the disease.
prion disease (1 paper, 2013). A transmissible disease that is caused by a protein that is able to induce abnormal folding of normal cellular proteins, leading to characteristic spongiform brain changes, which are associated with neuronal loss without an inflammatory response. "Only one of these genes, MT2A, had previously been reported to be associated with prion diseases." (PMID 23497022, 2013). "In conclusion, this study of gene transcription and protein expression and distribution confirm CAPN6, GALA1, MTNR1B and MT2A as potential targets for further prion disease research." (PMID 23497022, 2013).
tumor (55 papers, 2008 to 2025). "In this study, the high expression of MT2A in the cancer nest tended to associate with the depth of tumor invasion (p = 0.07)." (PMID 34572779, 2021). "The present work evaluates the effect of genetic polymorphisms in the MT2A core promoter region on the risk and tumor behavior of sinonasal Schneiderian papilloma in a Polish population." (PMID 26036762, 2015). "Among them, SSRP1 and SEPT2 that participate in cell cycle progression or MYCBP, HMGA1 and MT2A involved in cell growth and proliferation and previously linked to tumor progression." (PMID 24870930, 2014). "Large discrepancies in MT expression exist between different tumor types, and no distinct and reliable association exists between MT-1A and MT-2A expression in tumor tissues." (PMID 23947958, 2013). "Methylation of MT-1A and MT-2A in malignant mesothelioma was shown to be associated with tumor grade histology and lymph-node involvement." (PMID 23947958, 2013). "Furthermore, MT-2A has been considered a relevant prognostic marker in salivary gland tumors, associated with higher invasive activity of the neoplasms." (PMID 31936364, 2020). "In another Chinese population, Di et al17 reported that rs28366003 and rs10636 polymorphisms in MT2A had a correlation with BC risk; moreover, the relationship between this polymorphism and the histological grade might help us to judge tumor prognosis." (PMID 30924556, 2019). "MT2A polymorphismis closely correlated with neoplasm, implicated in laryngeal cancer." (PMID 27608012, 2016). "Moreover, it was demonstrated that enhanced susceptibility to neoplasm was related to aberrant expression of MT2A and Cd, Zn, Cu, and Pb content in biopsy neoplastic tissue." (PMID 26036762, 2015). "The goal of this study was to identify three SNPs at loci −5 A/G (rs28366003) and −209 A/G (rs1610216) in the core promoter region and at locus +838 C/G (rs10636) in 3′UTR region of the MT2A gene with IP risk and with tumor invasiveness according to Krouse staging." (PMID 26036762, 2015). "In conclusion, the present study revealed that the biochemical recurrence of PCa may be significantly associated with tumor cell proliferation status and loss of cell-cell adhesion, as reflected by MT-2A, cyclin-E expression and E-cadherin expression." (PMID 26622816, 2015). "Although clinicopathological parameters, such as risk classification and tumor stage, may be closely associated with the early biochemical recurrence of PCa, studies concerning the potential roles of MT-2A and cyclin E in predicting biochemical recurrence of PCa are limited." (PMID 26622816, 2015). "Our findings establish a copper-dependent MT2A trafficking to mitochondria as a therapeutic target that simultaneously sabotage metal homeostasis and metabolic reprogramming in breast malignancies." (PMID 41211480, 2025). "In the hypoxic tumor microenvironment, MT2A supports cancer cell survival by neutralizing oxidative stress and contributing to chemotherapy resistance." (PMID 41211480, 2025). "qRT-PCR revealed significant upregulation of CXCL10, CXCL11, ME1, MT1X, FAT1, OAS2, and MT2A in tumor tissues compared to normal tissues." (PMID 40574841, 2025). "According to the analysis of the online databases, the parental gene MT2A was also significantly decreased in HCC tumor tissues and was positively correlated with the pseudogene-derived MT2P1-RNA." (PMID 40407049, 2025). "MT2A can serve as a prognostic factor for assessing the risk of tumor severity as it is significantly associated with high tumor stage, LNM, high tumor grade, LVI, and PNI." (PMID 37801187, 2023). "In the subcutaneous tumor samples, IHC staining showed that overexpression of MT2A promoted the expression of phosphorylated MST1 and YAP1 compared to the control." (PMID 35642057, 2022). "No mutations in catechol-O-methyltransferase (COMT), fatty acid binding protein 4 (FABP4), myoglobin (MB) and metallothionein 2A (MT2A) were detected in COAD tumor tissues." (PMID 36203457, 2022).
tumor (continued). "The expression level of metallothionein 2A (MT2A), also known as MT2, is associated with tumor types." (PMID 35642057, 2022). "Since we determined MT2A as an antitumor gene and downregulated cell proliferation in vitro, we continued to assess the effect of MT2A on tumor growth in vivo." (PMID 36009228, 2022). "Metallothionein 2A (MT2A) was downregulated in the tumor tissues of patients with CRC compared to adjacent normal tissues and was related to the tumor M stage of patients." (PMID 35642057, 2022). "In this study, we reported that high expression of MT2A in the cancer stroma and cancer nest is involved in tumor progression in the ESCC microenvironment." (PMID 34572779, 2021). "Our findings also confirm another result, a positive correlation between MT-2A and MMP-9, suggesting the associated participation of these proteins in tumor invasion." (PMID 31936364, 2020). "In effect, we revealed a negative correlation between MT2A level and drug efficacy (IC50 values), and anti-tumour effects for various chemotherapeutic drugs when cells were silenced for MT2A." (PMID 31444479, 2019). "Taken together, these results confirm that MT2A level influence chemotherapy induced-cell death, and primary tumour development resulting in modulation of pulmonary metastatic dissemination." (PMID 31444479, 2019). "Four genes from the metallothionein cluster on human chromosome 16q13 (MT1A, MT1E, MT1M, MT2A) were overexpressed in 231_HM.LNm5 tumours only, thus placing them in the metastatic virulence category." (PMID 29720474, 2018). "Recent studies showed the expression of the Metallothionein 2A (MT2A) gene increased in some human neoplasms." (PMID 28228606, 2017). "We also analyzed the relationships between MT2A SNPs and clinical features of BC, including tumor size, lymph node metastasis, ER/PR/HER-2 status, his-tological grade, and venous invasion." (PMID 28228606, 2017). "MT-2A and cyclin E have been previously reported to be important modulators involved in tumor cell proliferation." (PMID 26622816, 2015). "MT2A is known to have anti-inflammatory, antiendotoxin, and tumor-inhibiting effects in cell cultures." (PMID 26881174, 2015). "MT2A exhibited an extensive positive correlation with tumor differentiation (P < 0.001) and inverse correlation with TNM stage (P = 0.05)." (PMID 23870553, 2013). "In HER2-positive disease, our findings associate genes such as ARG2, S100A1, MT2A, EIF4EBP1, KLF4, BTG3, and BAG1 to be associated with favourable prognosis through their roles in metabolic regulation, oxidative stress mitigation, and tumour suppression." (PMID 41007296, 2025). "As a representative gene, MT2A was queried across pan-cancer TCGA tumors in different tumor types." (PMID 39858588, 2025). "These coordinated changes suggest that MT2A may function as a hypoxia-responsive molecular effector, integrating transcriptional induction with subcellular translocation to mediate tumor adaptive responses in the hypoxic tumor microenvironment." (PMID 41211480, 2025). "This analysis may reflect a corresponding correlation between MT2A mitochondrial levels and tumor hypoxic status." (PMID 41211480, 2025). "The tumor size of MT2A-overexpressing cells was significantly smaller than that of control cells." (PMID 35642057, 2022). "In addition, the differential expression of MT2A also depends on tumor differentiation status as well as other environmental stimuli and gene mutations." (PMID 35642057, 2022). "In the present study, increased expression of phosphorylated Mst1, LATS2 and YAP1 was observed in CRC cells overexpressing MT2A, and similar results were also observed in subcutaneous CRC tumor and liver metastasis tissues overexpressing MT2A according to immunohistochemical staining." (PMID 35642057, 2022). "More importantly, we found that MT2A expression was associated with the tumor M and N phases but not the T phase." (PMID 35642057, 2022).
tumor (continued). "The discrepancy may be due to several reasons, such as: different splicing forms of MT2A or LATS2 proteins may have different roles in tumor development; different lengths of patient follow-up used in the survival analysis may yield different HRs, etc." (PMID 33839701, 2021). "In other words, the high expression of MT2A in ESCC cells may promote tumor progression and malignancy through the E-cadherin/β-catenin signaling pathway." (PMID 34572779, 2021). "However, we realize that our findings represent only one voice in an ongoing discussion and further studies of greater dimensions are required to determine the precise role of MT2A in the carcinogenicity and physiopathology of neoplastic diseases." (PMID 26036762, 2015). "Most of the data indicate that MT2A transcripts or, most often, protein expression in tumors may be involved in determining aggressive tumor behavior and increased patient mortality, however, many demonstrate equivocal results and divergent conclusions." (PMID 26036762, 2015). "Unfortunately, a literature survey reveals no publication describing the activity of MT2A isoforms and their relationship with the risk and tumor clinical behavior in sinonasal Schneiderian papillomas." (PMID 26036762, 2015). "MT2A is a low-molecular-weight protein in the cytoplasm, plays multiple roles in cell metabolism, and has the effects on anti-inflammation and antiendotoxin and inhibiting tumor growth." (PMID 26881174, 2015). "MT2A might play a tumor suppressive activity through inhibiting NF-κB signaling and may be a prognostic biomarker and potential target for individual therapy of GC patients." (PMID 23870553, 2013). "Furthermore, MT2A in ESCC cells may regulate the E-cadherin/β-catenin signaling pathway to promote tumor progression." (PMID 34572779, 2021). "Therefore, we hypothesized that MT2A in CAFs regulates the secretion of tumor-promoting humoral factors by activating specific intracellular signaling pathways." (PMID 34572779, 2021). "Therefore, we believed that abnormal expression of MT2A in tumor cells could affect cell survival outcome." (PMID 34220318, 2021). "The basal tumor cells of cSCC samples in our study highly expressed CCL2, CXCL14, FTH1, MT2A, which is consistent with the findings in Tumor_KC_Basal." (PMID 38099574, 2023). "The CAFs express high levels of metallothionein 2A (MT2A), which is necessary for their tumor-promoting effects." (PMID 37046676, 2023). "MT2A, TIMP1, and GFAP are more highly expressed in tumor cells and are down-regulated in the periphery." (PMID 35327982, 2022). "Phosphorylation of MST1 and LATS2 promoted by metallothionein 2A (MT2A) restrained the YAP1 nuclear localization, thereby preventing CRC from enhanced tumor growth and liver metastasis." (PMID 36289774, 2022). "Our results showed that the relative mRNA expression of ADIRF, MT2A, MT1M, and JUNB was downregulated after TGF-beta treatment and/or tumor stimulation, while the expression level of C11orf96 was upregulated, even after tumor stimulation." (PMID 33777046, 2021). "Some genes, such as MT2A, NEAT1, ATP1B1, and C11orf96, were highly expressed in tumour cells from ccRCC1." (PMID 34168986, 2021). "Finally, it has to be mentioned that the MT2A has differential outcome in various types of cancer that may be tissue or cell type dependent, just like E2 factor, including cellular proliferation, apoptosis and tumor kinetics." (PMID 27608012, 2016). "Thus, in the last half decade, research has been focused on the identification of the aftermath and the mechanisms through which the presence of SNPs in some genes, inter alia the MT2A gene, may induce a malignant cell phenotype and determine cell proliferation, growth and tumor invasion." (PMID 26036762, 2015). "Since apoptosis was a crucial mechanism through which cetuximab induced tumor cell death 30, MT1E and MT2A expression might correlate with enhanced drug sensitivity, while PCK1 and TGFBI expression might be linked to resistance." (PMID 40959565, 2025).
tumor (continued). "According to the marker genes, these clusters were designated as blood endothelial cells (FLT1; clusters 0–3, 5, 6), lymphatic endothelial cells (PDPN: cluster 4), tumor endothelial cells (HSPG2: clusters 0 and 2–6), and normal endothelial cells (MT2A; clusters 0–6)." (PMID 33083004, 2020). "In addition, MT2A/MT2 silencing using shRNA strategy led to a marked reduction of IC50 values and to enhanced cytotoxic effect of chemotherapy on primary tumour." (PMID 31444479, 2019). "Univariate analysis indicated that some factors including decreased MT2A expression (P < 0.001), TNM stage (P < 0.01), tumor depth (P < 0.05), lymph node status (P < 0.05), distant metastasis (P < 0.001) and degree of differentiation (P = 0.011) were correlated with poor survival." (PMID 23870553, 2013). "By the NF-B, AKT, and ERK signaling pathways, MT2A boosts the synthesis and release of IGFBP2 in CAF-like cells and encourages the migratory and invasive properties of ESCC cells.Additionally, MT2A takes part in tumour cell expansion, invasion and migration in ESCC." (PMID 37927475, 2023).
cancer (47 papers, 2008 to 2025). A tumor composed of atypical neoplastic, often pleomorphic cells that invade other tissues. "The single nucleotide polymorphisms at the MT2A gene have been associated in various human diseases including cancer." (PMID 36690679, 2023). "In this study, we also demonstrated that high expression of MT2A in the cancer nest is associated with poor prognosis of ESCC patients." (PMID 34572779, 2021). "Zn level was not considered in previous studies investigating association of MMP-1, MMP-2, MMP-7, MMP-13 and MT2A polymorphism with cancer risk." (PMID 32765800, 2020). "Rs28366003 and rs10636 polymorphisms are the most common loci of MT2A, having been found to be associated with many different cancers." (PMID 28228606, 2017). "MT2A has been implicated in the development of various cancers." (PMID 38987777, 2024). "Upregulation of BATF2 and downregulation of ISG15 and MT2A were reported to reduce cancer risk." (PMID 36077244, 2022). "Furthermore, some mt2a gene polymorphisms, including rs28366003 and rs1610216, are associated with an increased risk of cancer." (PMID 36060520, 2022). "Genetic polymorphisms of MT2A are frequently observed in many different cancers." (PMID 28228606, 2017). "The studies indicate that MT2A core promoter region genetic polymorphism and in particular confirmation although of one copy of the risk allele at rs28366003 in the MT2A gene may have an impact on cancer risk of various origins." (PMID 26036762, 2015). "In addition, MT2A polymorphism is associated with increased cancer risk." (PMID 35928229, 2022). "Here, we provide a new perspective on how cancer cells adapt to hypoxic microenvironment through mitochondrial MT2A." (PMID 41211480, 2025). "Recently, a published study has demonstrated that HIF-1α-induced MT2A accumulation can sequester mitochondrial copper to blunt apoptotic signaling, thereby promoting cancer cell resistance to cell death." (PMID 41211480, 2025). "The results of our RT-qPCR assays showed significant differences in MT2A mRNA levels between paired cancer tissues and normal tissues when using β-actin or 18S as the internal control." (PMID 36009228, 2022). "Higher mRNA expression levels of both ISG15 and MT2A, found in this study as downregulated in blood samples from children with ASD, were reported to be associated with worse cancer prognosis." (PMID 36077244, 2022). "Taken together, the upregulation of BATF2 and the downregulation of both ISG15 and MT2A, as reported here in blood samples from children with ASD, suggesting a reduced risk of cancer." (PMID 36077244, 2022). "In this regard, MT2A protein exerts its anti-cancer effects through inactivation of NFKBIA (NFKB Inhibitor Alpha) subsequent binding to MZF1 (Myeloid Zinc Finger 1)." (PMID 36060520, 2022). "To explore the underlying differences, we identified that MT2A was significantly downregulated in CRC in TCGA, GSE and Oncomine databases, and we confirmed this result in 65 pairs of cancer and adjacent tissues in patients with CRC." (PMID 35642057, 2022). "Immunohistochemistry demonstrated that high MT2A expression in the cancer stroma and cancer nest of ESCC tissues correlated with poor prognosis of ESCC patients." (PMID 34572779, 2021). "Recent studies confirmed that the presence of different MT isoforms, mostly metallothionein 2A (MT-2A), correlates with cell proliferation and clinicopathological behavior in some cancers." (PMID 31936364, 2020). "Again, only one gene is commonly altered across all four cancer cell lines: MT2A (Metallothionein 2A)." (PMID 27036029, 2016). "In this study, we offered both clinical and mechanistic evidence that MT2A is an independent prognostic factor and effective molecular target for cancer therapy." (PMID 23870553, 2013).